SLC2A1 (solute carrier family 2 member 1)
Diseases named in the same sentence as SLC2A1 in open-access papers (continued):
Sharing a sentence is not in itself a finding about the gene and the disease.
SLC2A1 also shares sentences with these, for which no sentence is quoted: hemangioma (33 papers); infantile hemangioma (25); Stroke (23); heart failure (21); esophageal cancer (19); brain tumors (17); nasopharyngeal carcinoma (16); type 1 diabetes (15); diabetic retinopathy (14); cardiac hypertrophy (13); COVID-19 (13); HIV-1 infection (13); triple-negative breast carcinoma (13); vascular malformation (12); esophageal squamous cell carcinoma (11); colorectal tumors (10); Encephalopathy (10); perineurioma (10); soft tissue sarcoma (10); vascular tumors (10); viral infection (10); gastrointestinal stromal tumor (9); gestational diabetes (9); pancreatic ductal adenocarcinoma (9); Parkinson disease (9); thymoma (9); Glucose intolerance (8); malaria (8); mesothelioma (8); mucinous carcinoma (8).
A further 506 diseases each share a sentence with SLC2A1 in 8 papers or fewer.